MYLK2 (myosin light chain kinase 2)
Description:
Ca(2+)/calmodulin-dependent kinase that phosphorylates the regulatory light chain (RLC) of sarcomeric myosin in skeletal and cardiac muscle. Phosphorylation of RLC promotes displacement of myosin cross-bridges from the thick filament backbone toward actin-containing thin filaments, increasing the probability of cross-bridge entry into force-generating states and thereby potentiating contractile force at submaximal Ca(2+) concentrations.
Synonyms: MLCK2; skMLCK; KMLC; MLCK
Tractability: Small molecule: a high-quality ligand is known; it belongs to a druggable protein family. PROTAC: ubiquitination databases record sites on it; a small molecule that binds it is known.
Target class: Kinase; CAMK protein kinase MLCK family; CAMK protein kinase group; Enzyme; Protein Kinase
Gene: Protein-coding gene on chromosome 20 (31,819,287 to 31,834,689, forward strand). Ensembl gene ENSG00000101306.
Subcellular location: Cytoplasm
Subcellular location (Human Protein Atlas): Endoplasmic reticulum
Gene Ontology:
Molecular function: myosin light chain kinase activity; protein binding; calcium/calmodulin-dependent protein kinase activity; calmodulin binding; myosin light chain binding; ATP binding; protein kinase activity
Biological process: cardiac muscle tissue morphogenesis; peptidyl-threonine phosphorylation; positive regulation of gene expression; protein autophosphorylation; regulation of muscle filament sliding; skeletal muscle cell differentiation; striated muscle contraction; cardiac muscle contraction; signal transduction; skeletal muscle satellite cell differentiation
Cellular component: cytoplasm; endoplasmic reticulum; nucleus; sarcomere
Genetic constraint (gnomAD): Loss-of-function variants: 27 observed, 58.62 expected, observed/expected ratio (o/e) 0.46, 90% interval 0.34 to 0.63. The upper end of that interval is the gene's LOEUF score, 0.63, which puts it in group 2 of 6, group 1 being the genes least tolerant of losing a copy. Missense variants: 676 observed, 795.32 expected, observed/expected ratio (o/e) 0.85, 90% interval 0.8 to 0.91. Synonymous variants: 310 observed, 308.22 expected, observed/expected ratio (o/e) 1.01, 90% interval 0.92 to 1.11.
Gene-disease validity (ClinGen):
ClinGen rates the evidence that MYLK2 causes each of these diseases.
hypertrophic cardiomyopathy (autosomal dominant): Disputed. A condition in which the myocardium is hypertrophied without an obvious cause.
Homologues: Orthologues: chimpanzee MYLK2 (99% identical), macaque MYLK2 (94% identical), dog MYLK2 (87% identical), guinea pig MYLK2 (84% identical), mouse Mylk2 (83% identical), pig MYLK2 (83% identical), rat Mylk2 (82% identical), rabbit MYLK2 (78% identical). Paralogues in human: MYLK3 (42% identical), MYLK4 (31% identical), DCLK2 (20% identical), DCLK1 (20% identical), DCLK3 (19% identical), CAMK1D (17% identical), CAMK2D (17% identical), CAMK2B (17% identical), CAMK2A (17% identical), PSKH1 (17% identical), CAMK1 (16% identical), CAMK2G (16% identical), and 10 more.
Diseases named in the same sentence as MYLK2 in open-access papers:
MYLK2 is named in the same sentence as 22 diseases in open-access papers, as found by Europe PMC text mining. Sharing a sentence is not in itself a finding about the gene and the disease. The quoted sentences say what the papers report.
cardiomyopathy (3 papers, 2017 to 2025). A disease of the heart muscle or myocardium proper. "MYLK2 is a kinase that, in adults, is expressed specifically in skeletal muscle, although inherited pathogenic mutations of its associated gene lead to cardiomyopathies." (PMID 40295335, 2025).
pancreatic cancer (3 papers, 2010 to 2023). "MYLK2 is a calcium/calmodulin dependent enzyme, and dysregulation of MYLK2 has been detected in several types of cancer, such as pancreatic cancer and colorectal cancer." (PMID 37309005, 2023). "Up-regulation of mannose-binding lectin 2 and myosin light chain kinase 2, which have not previously been implicated in pancreatic cancer, were observed." (PMID 20587030, 2010). "Mannose-binding lectin 2 and myosin light chain kinase 2, a serine/threonine kinase, were identified as potential biomarkers for the pancreatic cancer diagnosis and further validated by western blot in an independent set of sera from pancreatic cancer patients and normal controls." (PMID 23401773, 2013). "In an independent series of serum samples from 16 patients with pancreatic cancer and 16 non-cancer-bearing controls, increased levels of mannose-binding lectin 2 and myosin light chain kinase 2 were confirmed by western blot." (PMID 20587030, 2010).
diabetic cardiomyopathy (1 paper, 2016). Diabetic cardiomyopathy is a disorder of the heart muscle in people with diabetes. "In addition, decreased expression of the genes playing a role in contractility including troponin I, myosin light chain 7 and myosin light chain kinase 2 could lead to sarcomeric dysfunction and diabetic cardiomyopathy." (PMID 27496100, 2016).
heart failure (1 paper, 2016). Inability of the heart to pump blood at an adequate rate to meet tissue metabolic requirements. "The main findings of this study are that MYLK2 is diminished in heart failure, predicts response to LVAD therapy, and does not improve in advanced heart failure patients post LVAD who require transplantation." (PMID 27884156, 2016). "MYLK2 is diminished in heart failure, predicts response to LVAD therapy, and does not improve in advanced heart failure patients post LVAD who require transplantation." (PMID 27884156, 2016).
prostate carcinoma (1 paper, 2025). A carcinoma that arises from epithelial cells of the prostate gland. "We confirmed that MYLK2 was highly expressed in PRAD by qPCR of normal prostate epithelial cell line RWPE-1 as well as prostate cancer cell lines PC-3 and LNCaP clone FGC, and Western blotting (WB)." (PMID 40463716, 2025). "qPCR as well as Western blotting (WB) results showed that MYLK2 expression was relatively high in PC-3 and LNCap cells compared to the normal prostate cancer cell line RWPE-1." (PMID 40463716, 2025).
pulmonary hypertension (1 paper, 2014). Increased pressure within the pulmonary circulation due to lung or heart disorder. "Many genes are functionally related to high-altitude physiology, such as angiogenesis (RGCC), pulmonary hypertension remodeling (PLA2G12A), oxygen intake (C9ORF3), neural response (GRID1 and GRIN2B), melanin synthesis (MITF, PDGFRB and PIK3R3) and heart development (FOXS1, GAA and MYLK2)." (PMID 25270331, 2014).
type 2 diabetes (1 paper, 2025). "Importantly, a large number of sarcomeric proteins (such as myosin light chain kinase 2 [MYLK2], MYBPC2 and myosin light chain 4 [MYL4]) were downregulated in type 2 diabetes muscle fibres." (PMID 40295335, 2025). "As a skeletal muscle-specific protein, MYLK2 could be a promising target for the modulation of resting myosin states in type 2 diabetes and related metabolic diseases in a way that would not impact the adult heart." (PMID 40295335, 2025).
uterine cancer (1 paper, 2020). Primary or metastatic malignant neoplasm involving the uterine corpus and/or the cervix. "Given that ACTG1 and MYLK2 showed the greatest alteration frequency in uterine cancer, we sought to explore them further within uterine cancer subtypes." (PMID 33217970, 2020). "Given that ACTG1 and MYLK2 amplifications or overexpression were consistently observed in uterine cancers, we sought to analyze their potential as uterine cancer biomarkers." (PMID 33217970, 2020). "Overall, our analysis predicted potential regulatory roles for MYLK2 and ACTG1 in uterine cancers." (PMID 33217970, 2020). "To determine potential mechanisms of ACTG1 and MYLK2 gains, we also examined genomic instability through measurements of fraction of the genome altered (FGA) in uterine cancers with and without ACTG1 and MYLK2 gains." (PMID 33217970, 2020).
uterine carcinosarcoma (1 paper, 2020). A usually aggressive malignant neoplasm arising from the uterine corpus and less often the cervix. "Uterine carcinosarcomas (UCS) were the lineage with the greatest rates of genomic or transcript upregulation of MYLK2 and ACTG1, with Net Gain Scores of 0.21 and 0.14 respectively." (PMID 33217970, 2020). "ACTG1 and MYLK2 were gained (amplified and/or overexpressed) at 5~14% and 5~20%, respectively, in uterine mixed endometrial carcinoma (UMEC), uterine serous carcinoma (USC), uterine endometrioid carcinoma (UEC) and uterine carcinosarcoma (UCS)." (PMID 33217970, 2020).
cancer (5 papers, 2010 to 2025). A tumor composed of atypical neoplastic, often pleomorphic cells that invade other tissues. "Among the actomyosin genes, ACTG1 (cytoplasmic γ-actin) and MYLK2 (skeletal myosin light chain kinase) were consistently amplified or overexpressed across cancers." (PMID 33217970, 2020). "However, the role of MYLK2 in cancer progression has not been clarified." (PMID 40463716, 2025). "While these observations may dismiss the prognosis utilities of MYLK2, as well as other recurrently perturbed actomyosin genes, e.g., MYH6 and MYH7, the specific functions of these genes still require a detailed functional interrogation in uterine as well as other cancer models." (PMID 33217970, 2020).
tumor (3 papers, 2018 to 2025). "The MYLK2 gene, encoding a calcium/calmodulin-dependent myosin light chain kinase whose expression is normally down-regulated in tumor cells, was up-regulated following treatment with the A. graveolens extract." (PMID 30042356, 2018). "Given the role of the MYLK family family in tumour progression, we hypothesised that MYLK2 may play a key role in the development of PRAD and may serve as a marker of worsening prognosis in PRAD." (PMID 40463716, 2025). "Our analysis demonstrated that MYLK2, FAM83D, STC2, CCDC112, EPHX4 and MMP1 were differentially expressed between tumor and normal tissues, with higher expression in tumor tissues than in normal tissues (p < 0.0001)." (PMID 37309005, 2023).
myopathies (1 paper, 2021). "A similar pattern of MYLK2 expression was observed in a study evaluating broilers affected with deep pectoral myopathies, showing a similar expression profile of this gene across different myopathies." (PMID 34381378, 2021).
MYLK2 also shares sentences with these, for which no sentence is quoted: colorectal cancer (1 paper); dengue (1); diabetes (1); infectious disease (1); metabolic disease (1); muscular disease (1); neuromuscular disease (1); uterine corpus endometrial carcinoma (1); uterine endometrioid carcinoma (1); uterine serous carcinoma (1).